MIR563 (microRNA 563)
Synonyms: hsa-mir-563; MIRN563
Gene: MicroRNA gene on chromosome 3 (15,873,771 to 15,873,849, forward strand). Ensembl gene ENSG00000207815.
Gene Ontology:
Biological process: miRNA-mediated post-transcriptional gene silencing